CD80 (CD80 molecule)
Diseases named in the same sentence as CD80 in open-access papers (continued):
Sharing a sentence is not in itself a finding about the gene and the disease.
infection (continued). "After infection with H-1PV, the level of CD80 and CD86 rose 8-fold and CD83 2-fold." (PMID 31192129, 2019). "These cells showed a reduction in MHC II and CD80 expression following infection with T. cruzi." (PMID 28620374, 2017). "At day 14 post infection a mean of 25% of the mMDSCs and 43% of the gMDSCs expressed CD80." (PMID 28835242, 2017). "We showed that cultured primary human macrophages, upon infection with some representative pathogenic arenaviruses, failed to elevate the levels of activating markers CD80, CD86 and of cytokines (e.g., IFNβ, TNFα, IL-1β, IL-6, and IL-8)." (PMID 28498311, 2017). "Likewise, for Tcon cells to overcome Treg-imposed restraints and mount a protective response during infection, APCs must upregulate B7 molecules (CD80, CD86) in order to provide Tcon cells with strong costimulatory signals." (PMID 27242798, 2016). "However, bmMΦ did not react to R. typhi with the production of NO and inflammatory cytokines but only upregulated MHCI and CD80 expression upon infection in vitro." (PMID 27548618, 2016). "MΦ upregulated the expression of MHCI and CD80 48h after infection." (PMID 27548618, 2016). "When memory B cell subsets in these mice were assessed, we found as expected that the frequency of memory B cell population (i.e. CD19+GL7-Fas-CD80+PD-L2+) increased in the spleens of infected WT and Bam32-/- mice as the infection progressed (see S2 Fig for gating strategy)." (PMID 25875604, 2015). "The studies presented here utilize a recombinant HSV-1 virus constructed such that it expresses the CD80 gene (HSV-CD80) in an attempt to determine if CD80 expressed by this recombinant virus would bind to PD-L1 expressed on DCs and lead to productive infection and lysis of cells." (PMID 24475315, 2014). "This attachment and subsequent infection involves colocalization of CD80 to PD-L1 on DCs." (PMID 24475315, 2014). "CD80 plays a critical role in stimulation of T cells and subsequent control of infection." (PMID 24475315, 2014). "A significant depletion in the percentage of AMDC was observed at day 4 post-infection that was associated with a change in steady-state CD11b+ and CD11b− AMDC subset frequencies and significantly elevated CD40 and CD80 expression and that returned to baseline by day 14 post-infection." (PMID 25398128, 2014). "To investigate whether maturation is induced in BDCA1+ mDCs upon infection we determined expression levels of co-stimulatory (CD80 and CD86) and co-inhibitory (PDL1) molecules on their cell surface." (PMID 23638101, 2013). "Thus, infection of MDDC with Candida albicans augments HIV trans infection of T cells in relation to increases in expression of CD80 and CD86 on the DC." (PMID 24278768, 2013). "The down-modulation of CD80/CD86 in chronic phase of the infection suggests that mycobacteria may actively exploit this pathway to anergize the T cells." (PMID 22719245, 2012). "Therefore, to evaluate the level of expression of activation markers, poBMDC were stained for SLA-I, SLA-II and CD80/86 after infection with SW114 or Nagasaki." (PMID 23157617, 2012). "The percentage of CD80+ pDCs also increased to a peak at day 15 (16.09±3.70%) and showed a significant increase at day 48 (13.44±2.35%, P = 0.021), when compared with that before infection (4.07±1.19%)." (PMID 22174949, 2011). "Therefore, the lower levels of CD86 and CD80 observed may be due to an abrogation of their induction following ZH501 infection." (PMID 38392897, 2024). "Moreover, in vitro and in vivo studies have shown that increased expression of CD80 and concomitant decreased expression of CD86 are associated with a more severe infection and inflammation, whereas increased expression of CD86 in septic patients is thought to have a protective function." (PMID 37213504, 2023).
infection (continued). "They concluded that the role of CD80 activation in the secretion of cytokines could be the main mechanism which decides whether the infection is cleared or will produce a pathological response with the latter response the most likely in the cervix of the low fertility Suffolk breed." (PMID 35546662, 2022). "All tissue sections at 4, 12 and 26 weeks from the decellularised pSFT and oSFT were devoid of CD80+ and CD 19+ cells, only the occasional positive cell was identified in the inflammatory infiltrate of tissue from the one 26-week decellularised pSFT which was suspected of having an infection." (PMID 34736146, 2021). "Similar to other DC subsets, these cells were susceptible to infection with hRSV, and while they expressed increased amounts of CD80 and CD86 in response to this virus as compared to non-infected cells, they also expressed the inhibitory costimulatory receptor PD-L1 and secreted IL-10." (PMID 31057543, 2019). "Blocking the CD28 ligands CD80 and CD86 in B6 mice reproduced the CD28ko phenotype following MmuPV1 infection and markedly reduced CD28 expression, implicating the CD28-CD80/CD86 axis in delayed viral clearance." (PMID 41805718, 2026). "Although classical co-stimulatory molecules such as CD80 and CD8613,18,41,42 are expressed at low levels, CD40 is upregulated on PMVECs after infection, as confirmed in vivo and in vitro." (PMID 41542053, 2026). "By day 7 post-infection, both the oseltamivir and MXSGD groups exhibited a significant decrease in CD80 expression (P < 0.01)." (PMID 40959060, 2025). "We also demonstrated the RSV infection-induced activation of monocytes via the expression of CD80, CD86, and HLA-DR on the cell surface upon infection." (PMID 41280933, 2025). "During infection in infants, monocytes are activated, leading to the upregulation of CD40, CD80, and MHC-I/II, which are involved in antigen presentation." (PMID 41280933, 2025). "Cell membrane markers typically expressed on monocytes/macrophages upon inflammation/infection (CD14, CD44, CD200), M1-polarization (CD80) and M2-polarization (CD163) were analyzed in the hemocyte population isolated." (PMID 38191588, 2024). "It was shown that under hypoxia, there is a reduction in CD80 and CD86 expression and an increase in the production of IL-12p70, which has an impact in the control of the infection of DC with L. amazonensis." (PMID 38787051, 2024). "D609‐treated BMDCs exhibited a significant reduction in the mean fluorescence intensities of costimulatory molecules, including CD80, CD86, CD40, and the differences in the reduced levels of costimulatory molecules were more pronounced after infection." (PMID 39692711, 2024). "rBCG-Rv1002c infection significantly upregulated immune regulatory molecules on the macrophage surface, including CD40, CD80, CD86, and MHC-II." (PMID 38932351, 2024). "As for some DZ signature genes, the LZ biomarker CD83 is downregulated upon infection in ensemble experiments but retained in EBV+ subsets co-expressing BCL2A1 (BFL-1) and other GC LZ hallmarks (CD80, CD86, and MYC)." (PMID 38059622, 2024). "We previously reported that MP-12 infection significantly increased expression of activation markers CD86 and CD80 on the surface of microglia." (PMID 38392897, 2024). "Our approach is based on the detection in isolated hemocytes from G. mellonella hemolymph of cell membrane markers typically expressed by human immune cells upon inflammation and infection, for instance CD14, CD44, CD80, CD163 and CD200." (PMID 38191588, 2024). "The mRNA expression levels of CD80, CD274, and CD28 in the liver were increased at 6 w after infection, which was consistent with the sequencing results." (PMID 39590301, 2024). "In particular, splenic cDC expressed higher levels of CD40, CD80, and CD86 from 4 h to 48 h post-infection compared with 0 h, especially at 4 h, with values of 21.1% ± 5.3 (p = 0.028), 48.1% ± 5.0 (p = 0.018), and 36.2% ± 3.1 (p = 0.009), respectively." (PMID 36977141, 2023).
infection (continued). "While expression of CD80 (B7-1) and PDL1 was continuously upregulated throughout infection, CD86 (B7-2) expression increased initially at D4 but dropped by 0.41-fold at D8." (PMID 37146079, 2023). "The dynamics and interaction between CD4+CD25+ and co-stimulatory molecules such as CD28, CD80, CD40 and CD40LG during infection with A. phagocytophilum in sheep needs further investigation in the future." (PMID 37989861, 2023). "After 24-h infection, the expression levels of CD83 and CD80 on MoDCs-P were found to be significantly lower than those on MoDCs-NP." (PMID 37983293, 2023). "And we also investigated the expression of cell-surface markers in splenic MΦs, the results showed that the levels of CD40, CD80 and CD86 both increased significantly at 96 h following i.v infection." (PMID 38012553, 2023). "This need for CD80 and CD86 in the pro-inflammatory response to S. aureus was evident early in the infection and in vitro using bone-marrow-derived macrophages." (PMID 37004108, 2023). "DC infection with 5448AP resulted in significantly reduced expression of MHC II, CD80, and CD86 in comparison to infection with 5448 (P < 0.05 to 0.01) (respectively)." (PMID 36744883, 2023). "Although the proportion of CD80+CD86+ B cells increased, class switching failure appeared in SFTSV infection patients." (PMID 37033979, 2023). "We observed that upon BPM treatment, the innate cells expressing co-stimulatory and activation markers, such as CD80, CD86, and CD40, were enhanced at the primary site of infection, i.e., lungs." (PMID 37272833, 2023). "On the other hand, infection with all GBS isolates significantly increased the expression of macrophage co-stimulatory molecules, CD80 and CD86 (middle and right)." (PMID 37213504, 2023). "The effects of exogenous vitamin D3 treatment on macrophage polarization markers CD80 and CD163 following infection with MAP for 24 hrs in vitro were assessed using immunocytochemistry and confocal microscopy." (PMID 36275033, 2022). "Of note, MP activation 36 hr post-infection, as measured by cell-surface modulation of MHC-II, CD80, ICAM-1, and Sca-1, was mostly comparable in all infected groups, likely ruling out a general activation defect of STING-deficient MP." (PMID 36278864, 2022). "(G) Quantification of median fluorescence values of co-stimulatory molecules (CD40, CD80, and CD86) on WT DCs stimulated with ON (black) or ON after pre-treatment of DCs with 50 mM FK506 for 20 min prior to infection (green)." (PMID 35881547, 2022). "Professional hematopoietic APCs upregulate MHCII and costimulatory receptors (CD40, CD80, and CD86) under inflammatory conditions triggered by infection, injury, and/or stress." (PMID 36227687, 2022). "The results showed that the levels of the M1-type membrane molecules CD80 and CD86 were increased on human dMφ after infection with T. gondii, while the levels of the M2-type membrane molecules CD206 and CD163 were decreased." (PMID 36514159, 2022). "The costimulatory molecules, CD80 and CD86, were suppressed due to infection with M. s_Rv1515c, pointing to the role of Rv1515c in dampening the costimulatory signals required for T cell activation." (PMID 35813825, 2022). "We also showed that infection with a KOS-ICP22Δ40 mutant virus resulted in higher levels of virus replication in the eye than seen after infection with ICP22 null virus and enhanced CD80 expression in dendritic cells." (PMID 36094100, 2022). "Compared to saline-Fc treated mice, Sema3E-Fc treated WT, and Sema3E KO mice showed higher MHC‐II, CD40, CD80, and CD86 molecules on the surface of DCs following infection." (PMID 35983029, 2022). "First, DC isolated from SND1-/- mice exhibited significantly lower CD40/CD80/CD86 expression and IL-12 production, but higher IL-10 production than wild-type mice during Cm infection." (PMID 33635920, 2021).
infection (continued). "More γδT cells were expressing CD80, CD11b, or PD-1 post-infection (p < 0.05), while less γδT cells were expressing CD34, CD62L, and CD127 post-infection (p < 0.05)." (PMID 33588839, 2021). "Treated and untreated infected mice were sacrificed 96 hours and 2 weeks after infection, their lungs removed, macerated and CD11c+ lung myeloid cells analyzed by flow cytometry for the expression of activation markers (IAb, CD40, CD80, and CD86)." (PMID 33936043, 2021). "The infection of BALB/c mice with L. donovani parasite resulted in increased intercellular adhesion molecule 1 (ICAM-1) and B7-1 (CD80) expression by infected macrophages." (PMID 33680991, 2021). "S. Typhimurium-infected chMoDCs showed significant upregulation in the expression of costimulatory (CD40, CD80, CD83 and CD86) and MHC molecules at 6 h post-infection in comparison to S. Gallinarum." (PMID 34446765, 2021). "Splenic SND1-/- DCs showed lower expression of CD40, CD80 and CD86 molecules than splenic wild-type DCs especially at day 7 following infection both in frequency and mean fluorescence intensity." (PMID 33635920, 2021). "The increased expression of CD40, CD54, CD80, CD86, and MHCII in DC2.4 dendritic cell line has been reported after infection with M. smegmatis and M. bovis BCG expressing an epitope from ovalbumin." (PMID 33260418, 2020). "Resting and IFNγ-treated macrophages were infected with B. cenocepacia and the expression of class I and II MHC molecules, CD80, and CD86 was quantified at 24 h post-infection." (PMID 32873215, 2020). "Similarly, while steady state levels of CD86 and CD80 on splenic cDCs derived from WT and BCAP-deficient mice were comparable, their expression on splenic cDCs from BCAP-deficient mice were much higher than that from WT mice following infection with Escherichia coli DH5α." (PMID 32133012, 2020). "We observed that the expression of CD25, MHCII, CD80, and PDL1 was significantly increased after infection (P < 0.05)." (PMID 32582168, 2020). "Using a HAdV-C5 chimera vector with the fiber knob of HAdV-B3 that bound to CD80 or CD86 instead of CAR, enhanced infection of these glioma cells." (PMID 32957644, 2020). "Mean fluorescence intensity signifying the estimate of surface expression of CD80, CD86, CD40, MHC I, and MHC II on macrophages increased significantly upon infection with Ms_Rv1954A as compared to Ms_Vc." (PMID 33163415, 2020). "Increased CD86 expression has been observed in a somewhat similar chronic, hepatotropic infection with HBV, where liver lobules were found to have a higher total count and percentage of CD86+ macrophages, compared to CD80+ or PD-L1+ macrophages." (PMID 31027182, 2019). "The infection group showed a notable increase in the expression of CD40, CD80, CD86, and MHC class II." (PMID 30791397, 2019). "In the blocked group, BMDC surface markers CD80, CD86, and MHC class II were significantly reduced in comparison with the infection group." (PMID 30791397, 2019). "At day 3 post-infection, CD11b+ DCs from CD11ccreIL-4Rα−/lox and littermate control mice showed equivalent expression of MHCII and CD80, demonstrating that early activation of DCs was unaltered in the absence of IL-4Rα expression." (PMID 32039054, 2019). "The results showed that RHΔrop16 infection induced higher expression of CD86 and CD80 but lower expression of CD206 on the surface of placental macrophages, when compared to the RH WT infection group." (PMID 32082272, 2019). "Similar results were reported in the context of Strongyloides stercoralis infection model in which it was observed an expressive increase of the CD80 molecule, along with MHC-II in eosinophils upon infection." (PMID 29445372, 2018). "In order to better understand the effect on infection and treatment on monocyte activation status, we measured the percentage of MHC class II (SLA DR)+ and CD80+ monocyte and granulocyte populations." (PMID 30072754, 2018).
infection (continued). "After resolution of infection (155-170dpi), the numbers of CD80+CD273+ and CD80+CD273— MSP121-specific B cells were either sustained or increased, while the CD80—CD273+ population decreased, compared with 28-35dpi." (PMID 30387712, 2018). "Both CD80 and CD86 were down-regulated on B cells following infection with the SV40 mutant strain 776-2E-SM1." (PMID 29432481, 2018). "Furthermore, the infection of activated cells induced production of cytokines known as deactivating factors for macrophage like TGF-β and IL-10, that when associated with decreased expression of MHC II and CD80 represent a powerful mechanism to modulate parasite growth in this cell line." (PMID 28620374, 2017). "The MHC II and CD80 expression was increased in LPS and IFN-γ stimulated cells, while infection by T. cruzi affected the ability of previously activated cells to increase MHC II and CD80 expression in DH82 cells." (PMID 28620374, 2017). "To determine macrophage activation under conditions of sustained p55TNFR presence, we analyzed the frequencies of CD11b+MHC-II+ cells as well as the MFIs of cell surface MHC-II, CD80 and CD86 expression on CD11b+ cells in the lungs at 21 days post-infection." (PMID 27995986, 2016). "The pDCs in PLN showed increased MHC I expression on days 3 and 4 post infection, decreased MHC II expression on days 4 and 5 and unaltered expression of CD80 and CD86." (PMID 27405244, 2016). "The results revealed that the expression of CD11c, CD80, CD86, MHC class II, and CCR7 was increased 7 days post-infection." (PMID 27279150, 2016). "Concerning infection with L. braziliensis, data from literature showed that CD14+ monocytes of peripheral blood from CL patients had a decreased expression of CD80 and CD86 following culture with media only or after restimulation with Leishmania antigen." (PMID 27536300, 2016). "After infection with the H9N2 virus for 24 h, the CD86, CD80, and CD40 expression levels in the DCs were significantly increased compared to the untreated group." (PMID 27826541, 2016). "Briefly, at 48 hours post infection (hpi), 78.7% of WNVNY99-infected MoDCs and 84.5% of WNVNSW2011-infected MoDCs showed CD80 upregulation, and 93.9% of WNVNY99-infected MoDCs, 95.8% of WNVNSW2011-infected MoDCs showed CD86 upregulation." (PMID 25884341, 2015). "To test the maturation status of NSR infected DCs, we analysed surface expression of MHC-I, MHC-II, CD40, CD80, CD83 and CD86 molecules upon infection." (PMID 26575844, 2015). "AmB treatment particularly enhanced the CD80 and CD86 expression up to 53% (P < 0.001) and 22.8% (P < 0.01), respectively with respect to infection control." (PMID 25884649, 2015). "At different times after infection, we gated on CD19+GL7-Fas- cells and assessed their co-expression of PD-L2 and CD80 molecules, markers previously used to delineate memory B cells." (PMID 25875604, 2015). "In vitro studies showed that infection of porcine BMDCs with rHuN4-GM-CSF resulted in increased surface expression of MHCI+, MHCII + and CD80/86+ that was dependent on virus expressed GM-CSF." (PMID 25420583, 2014). "MDCs showed up-regulations of the maturation markers CD80 and CD86 in blood and LN at early time points of primary infection (in blood: p = 0.008 at day 4 pi for CD86 and p = 0.008 at day 2 pi for CD80, in LNs: p = 0.031 at day 9 for CD80)." (PMID 24991927, 2014). "We further find that DENV infection blocked the expression of activation markers CD80 and CD86 on monocytes, DCs and MΦs in the dermis and that this effect was more pronounced during ADE compared to 1° infection." (PMID 25474197, 2014). "We asked about the age-dependent expression of the costimulatory molecules CD86, CD80 and CD70 on the surface of CD103+ and CD11b+ DCs in the MLN at three days post-infection with RSV as an indication of their capacity to effectively induce adaptive responses." (PMID 24550729, 2014).